CXCL1 (C-X-C motif chemokine ligand 1)
Diseases named in the same sentence as CXCL1 in open-access papers (continued):
Sharing a sentence is not in itself a finding about the gene and the disease.
ovarian carcinoma (continued). "Our observations might bring new insights into ovarian cancer progression and revealed a novel mechanism by which miR-27b-5p regulated the proliferation and malignant metastatic phenotypes of ovarian carcinoma cell via targeting CXCL1." (PMID 32782028, 2020). "Moreover, in ovarian cancer, stromal cells, surrounding the tumor, release CXCL1, CXCL2 and CXCL8 exerting a chemoprotective role on cancer cells and contributing to polarize monocyte/macrophage toward an M2 tumor promoting phenotype." (PMID 33066172, 2020). "In conclusion, we demonstrated the associations of CXCL1 variants rs11547681 with the risk of ovarian cancer in the Chinese Han population and updated our understanding on 5’UTR for CXCL1 functions, providing new information on the pathogenesis of cancers especially ovarian cancer." (PMID 32326946, 2020). "Finally, an inversely correlation between miR-27b-5p and CXCL1 in ovarian cancer tissue was confirmed through Spearman’s correlation analysis." (PMID 32782028, 2020). "In addition, CXCL1 was ascertained as a downstream target of miR-27b-5p in ovarian cancer and restoring CXCL1 expression counteracted the suppressive effects of miR-27b-5p." (PMID 32782028, 2020). "Altogether, miR-27b-5p repressed the progression of ovarian carcinoma through regulating CXCL1." (PMID 32782028, 2020). "C-X-C motif chemokine ligand 1 (CXCL1) defects may facilitate inflammation and transactivate EGFR in ovarian cancer, but the precise haplotypes associated with the potential diseases remained largely unknown." (PMID 32326946, 2020). "Previous study reported that circulating CXCL1 combining CCL18 could be as tumor markers for the differential diagnosis between ovarian cancer and benign ovarian masses." (PMID 31998654, 2019). "Previously, we demonstrated that EGF or TNF could induce the expression of proinflammatory chemokines such as CXCL1, 2, 3 and 8 in ovarian cancer cells via NF-κB, Akt and Erk signaling pathways." (PMID 30034618, 2018). "Furthermore, as described in detail previously, CXCR2 positive ovarian cancer cells enhanced more the promoter activity and mRNA levels of CXCL1 and 2 by NF-κB potentiation through EGFR-activated Akt compared to CXCR2 negative cells." (PMID 27723802, 2016). "Our recent studies in endometrial and ovarian cancer suggested that CXCL1 and/or CXCL8 secreted by human cancer cells and signalling via their receptors CXCR1 and/or CXCR2 could be implicated in human ASC migration." (PMID 27241286, 2016). "Together, these findings suggest that overexpression of GAB2 in ovarian cancers may contribute to upregulation of CXCL1, CXCL2 and CXCL8 expression in a context specific manner." (PMID 26657155, 2016). "Additionally, miR-200a and miR-200b have also been shown to directly target the pro-angiogenic ligands interleukin 8 (IL-8) and chemokine (C-X-C motif) ligand 1 (CXCL1) to regulate angiogenesis in ovarian cancer." (PMID 25762624, 2015). "CXCL1 also induced proliferation in epithelial ovarian cancer cells." (PMID 24376747, 2013). "Activation of the CXCL1/2-CXCR2 axis could therefore augment the clinical features of ovarian cancer such as peritoneal tumor dissemination and ascites leading to higher mortality rates." (PMID 24376747, 2013). "While its activation in TAMs can reprogram them toward an anti-tumor M1 phenotype, its activation in ovarian cancer cells—via CXCL1, MIP-1β, MCP-1, TNF-α, and RANTES, or other secreted factors might be involved in driving metastasis, immune suppression, and therapy resistance." (PMID 40330466, 2025). "CXCL1 may play a significant role in ovarian cancer metastasis." (PMID 37108425, 2023). "Additionally, we verified that CXCL1 was a target of miR-27b-5p in ovarian carcinoma cells." (PMID 32782028, 2020).
ovarian carcinoma (continued). "Moreover, ovarian cancer chemokines such as IL-8 and CXCL-1 and stemness marker OCT4 were suppressed by NAG-1 in SKOV3 cells, indicating that NAG-1 expression positively regulates not only pro-inflammatory signals but also cancer stemness biomarkers in MyD88-positive type I EOC cells." (PMID 27708225, 2016). "Therefore inhibition of the CXCL1/2-CXCR2 axis may be an effective preventive or therapeutic action against CXCR2-driven ovarian cancer progression." (PMID 24376747, 2013). "In a cultured cell line derived from the ascites of a patient with platinum resistant ovarian cancer (ET2), elevated levels of CCL2, CCL3, CCL4, CCL5, CXCL1, CXCL8 and CXCL10 were detected in the cultured media." (PMID 41424784, 2025). "Higher serum CXCL1 levels are a marker of resistance to carboplatin in patients with high-grade serous ovarian carcinoma (HGSOC) and ovarian cancer." (PMID 37108425, 2023). "Our results align with these findings and show that CXCL1, CXCL5, CXCL8, and CXCL11 are overexpressed in ovarian cancer." (PMID 36969851, 2023). "In ovarian cancers specifically, CAFs can induce angiogenesis through the secretion of IL-6, COX-2, and CXCL1, while ovarian cancer cells are reported to induce CAFs to secrete CXCL12, IL-6, and VEGF-A expression via HOXA9, leading to angiogenesis." (PMID 36672620, 2023). "We also found that catecholamines induce the secretion of CXCL1 and CXCL8 and increase ovarian cancer cell invasion by interacting with their corresponding receptors, which can be disrupted by specific inhibitors." (PMID 37762405, 2023). "For instance, CXCL1 and CXCL8 have been found to stimulate ovarian cancer cell growth via activation of the p38 and Wnt/β-catenin pathway." (PMID 36969851, 2023). "The results showed that the levels of CXCL1 and CXCL8 in the plasma of ovarian cancer patients were significantly increased compared to healthy subjects." (PMID 37762405, 2023). "CXCL1 is also important in the migration and EMT of ovarian cancer cells, which is related to the increased expression of MMP2 and MMP9 by CXCL1." (PMID 37108425, 2023). "The chemokine CXCL1, also known as growth-related oncogene (GRO)-α, has been found to be upregulated in ovarian cancer and promotes tumor growth and invasion." (PMID 37762405, 2023). "We identified CXCL1 and CXCL8 as chemokines induced by epinephrine and confirmed that their secretion in ovarian cancer cells increased in a dose-dependent manner following treatment with epinephrine, norepinephrine, and isoproterenol." (PMID 37762405, 2023). "CXCL1 and CXCL8 chemokines secreted by ovarian cancer cells bind to CXCR1 and CXCR2 receptors and promote cell proliferation, migration, and angiogenesis." (PMID 37762405, 2023). "Our results showed that CXCL1, CXCL8, CXCL9, CXCL11, CXCL12, CXCL16, and CXCL17 were remarkably elevated in ovarian cancer compared to those in normal tissue." (PMID 33763130, 2021). "The transcriptional levels of CXCL1, CXCL8, CXCL10, CXCL11, CXCL12, CXCL13, and CXCL14 were significantly elevated while CXCL3 was obviously reduced in ovarian cancer vs normal ovarian tissue." (PMID 33763130, 2021). "Ovarian cancer CAFs can indirectly induce angiogenesis through increased secretion of pro-inflammatory factors IL-6, COX-2, and CXCL1." (PMID 30380628, 2018). "In ovarian cancer, RAS-induced CXCL1 can be a potent inducer of senescence in stromal fibroblasts, showing the possibility of diagnostic marker and therapeutic target of CXCL1." (PMID 29360827, 2018). "In ovarian cancer, overexpression of miR-200c in an ovarian cancer cell line (Hey8A) decreased IL8 and CXCL1 expressions." (PMID 28587302, 2017). "Previous studies suggest that IKKβ regulates the expression of CXCL1, CXCL2 and CXCL8 in ovarian cancer cells." (PMID 26657155, 2016). "In terms of ovarian cancer, overexpression of miR-200c in an ovarian cancer cell line (Hey8A) decreased IL8 and CXCL1 expressions and this suppression was reversed by the presence of miR-200c inhibitors." (PMID 27601996, 2016).
ovarian carcinoma (continued). "In this report we show that senescent human peritoneal mesothelial cells (HPMCs) alter the secretory profile of ovarian cancer cells (A2780, OVCAR-3, SKOV-3) by increasing the release of four angiogenic agents: CXCL1, CXCL8, HGF, and VEGF." (PMID 26433963, 2016). "We showed that inhibition of IKKβ by both genetic and pharmacological means effectively reduced the transcription of CXCL1, CXCL2 and CXCL8 in GAB2-overexpressing FTSECs and ovarian cancer cells." (PMID 26657155, 2016). "In our recent study, potentiating NF-κB activation through EGFR-transactivated Akt augmented proinflammatory chemokines CXCL1/2, contributing to CXCR2-driven ovarian cancer progression." (PMID 27723802, 2016). "Unexpectedly, CXCR2 ligands such as CXCL1-3 and 8 were decreased in the progression of CXCR2-driven ovarian cancer compared to relatively constant CCL20 levels." (PMID 27723802, 2016). "These facts support the expectation that NF-κB is mainly involved in the progression of CXCR2-driven ovarian cancer, leading to augmentation of CXCR2 ligands such as CXCL1-3 and 5–8 followed by proinflammatory tumor microenvironment via CXCR2 axis." (PMID 27723802, 2016). "Our previous study demonstrated that proinflammatory chemokines such as CCL20, CXCL1-3 and CXCL8 are elicited in ovarian cancer cells via NF-κB- and EGFR-activated signaling pathways." (PMID 27723802, 2016). "The underlying mechanisms likely involve the NFκB-regulated chemokine expression, since several studies have demonstrated that the expression of CCL2, CXCL1, CXCL2, and IL-8/CXCL8 is mediated by NFκB in ovarian cancer cells." (PMID 25790431, 2015). "CXCL1 selectively binds to CXCR2, a G-protein-coupled receptor (GPCR) that has been shown to transactivate EGFR in ovarian cancer and non-small cell lung cancer." (PMID 26462152, 2015). "The chemokine network revealed that ovarian cancer cells commonly expressed high levels of proinflammatory chemokines such as CCL20, CXCL1-3 and CXCL8 in response to EGF or TNF." (PMID 23800251, 2013). "The fact that an EGF-induced increase in CXCL1 and CXCL8 was decreased by MAPK inhibitors in ovarian cancer cells indicates involvement of Akt or Erk signaling." (PMID 23800251, 2013). "Our results indicate that ovarian cancer cells induce CCL20, CXCL1-3 and CXCL8 as the primary chemokines in response to EGF or TNF." (PMID 23800251, 2013). "CXCL1 and CXCL8, in particular, have been identified as secreted proteins regulated by EGF and the PI3K pathway in ovarian cancer cell lines." (PMID 23800251, 2013). "The results revealed high expression of chemokines in the following ovarian cancer cell lines: CCL20 and 28, CXCL1, 2, 3 and 8 in OVCAR-3 cells; CCL28 and CXCL1 in SKOV-3 cells; CXCL1, 2 and 8 in CaOV-3 cells; and CXCL2 in TOV-21G cells." (PMID 23300534, 2012). "In combination with CXCL1, CCL18 monitoring outperformed CA125 as a circulating ovarian cancer biomarker." (PMID 22629457, 2012). "CXCL1 and CXCL8 were identified as being distinctive ovarian cancer markers." (PMID 40507922, 2025). "Adiponectin enhances CXCL1 secretion, which, in turn, promotes VEGF secretion and angiogenesis in various cancers, including colon and ovarian cancer." (PMID 38813109, 2024). "Among them, the research results of CXCL1 and CXCL2 in epithelial ovarian cancer and other tumors have shown that they are related to the malignant biology of the tumor, and they have higher regression coefficients in the model, which has the most significant impact on the prediction model." (PMID 38509620, 2024). "Finally, we found that the concentration of CXCL1 and CXCL8 in the plasma of ovarian cancer patients increased with stage progression." (PMID 37762405, 2023). "Moreover, we analyzed the plasma levels of CXCL1 and CXCL8 in ovarian cancer patients at various stages of the disease and observed a significant increase in their levels with disease progression." (PMID 37762405, 2023).
ovarian carcinoma (continued). "Although CXCL1 expression is found in a significant number of ovarian carcinoma cases, its role can be largely played by CXCL8/IL-8, whose expression is found in all cases of ovarian carcinomas." (PMID 37108425, 2023). "As in murine models of ovarian cancer, MDSC production could be stimulated by various tumor-derived factors: CXCL1/2, G-CSF, GM-CSF, VEGF, and PGE2." (PMID 33562495, 2021). "We next determined whether CXCL1, CXCL2 and CXCL8 were required for proliferation and survival of ovarian cancer cells with GAB2 overexpression." (PMID 26657155, 2016). "Taken together, in consonance with previous observations, our results suggest that CXCL1, CXCL2 and CXCL8 could act as autocrine growth factors that directly promote proliferation and survival of ovarian cancer cells that overexpressed GAB2." (PMID 26657155, 2016). "Indeed, we showed that inhibition of IKKβ not only significantly reduced expression of CXCL1, CXCL2 and CXCL8, but also suppressed clonogenic growth of ovarian cancer cells as a single agent." (PMID 26657155, 2016). "In addition, CXCL1, CXCL2, and CXCL5 (ENA-78) can stimulate cell proliferation and migration in ovarian cancer." (PMID 26414070, 2015). "These experimental findings are supported by clinical data showing that CXCL1 expression levels are greater in ovarian cancer than in normal ovary tissues and are also higher in sera from women with ovarian cancer." (PMID 23800251, 2013). "Thus augmentation of proinflammatory chemokines CXCL1/2, by potentiating NF-κB activation through EGFR-transactivated Akt, contributes to CXCR2-driven ovarian cancer progression." (PMID 24376747, 2013). "A primary finding of this study is that CXCR2-driven cancer progression involves upregulation of its own ligands such as CXCL1 and CXCL2 by potentiating NF-κB activation via EGFR-transactivated Akt signaling followed by accelerated ovarian cancer cell proliferation, migration and invasion." (PMID 24376747, 2013). "Furthermore, we measured the expression of receptors for CXCL1 and CXCL8 in ovarian cancer cells and demonstrated that specific antibodies, receptor inhibitors, and CXCL8 antibodies SB225002 and SB265610, significantly inhibited ovarian cancer cell invasion induced by epinephrine." (PMID 37762405, 2023). "Therefore, we conclude that the development of targeted molecules to inhibit CXCL1 and CXCL8 may be a promising strategy for suppressing ovarian cancer progression and achieving therapeutic benefits." (PMID 37762405, 2023). "For this reason, both CXCL1 and CCL18 may be used as biomarkers in the diagnosis of ovarian cancer." (PMID 37108425, 2023). "Finally, we investigated the effect of CXCL1 and CXCL2 in clinical ovarian cancer samples." (PMID 29703902, 2018). "To examine whether high GAB2 levels in ovarian cancer cells are required for expression of CXCL1, CXCL2 and CXCL8, we suppressed GAB2 with inducible shRNAs in FUOV1 cells and observed that induced suppression of GAB2 decreased the mRNA levels of CXCL1, CXCL2 and CXCL8 compared with un-induced cells." (PMID 26657155, 2016). "It was determined that CCL18 and CXCL1 had a high sensitivity for ovarian cancer diagnosis, but the specificity was not satisfactory; however, C1D, TM4SF1, TIZ, and FXR1 had a high specificity compared with a combination of CCL18 and CXCL1." (PMID 33672007, 2021). "CXCR2 is activated by cancer-promoting IL-8 and CXCL1 and could transactivate EGFR in ovarian cancer and non-small cell lung cancer." (PMID 26462152, 2015).
Sepsis (70 papers, 2009 to 2026). Sepsis is defined as life-threatening organ dysfunction caused by a dysregulated host response to infection. "We opted for a ready-made reagent kit for cytokine analysis, which led to the omission of several well-recognized cytokines associated with sepsis progression, such as CXCL-1, IL-18, IL-26, and IL-27." (PMID 38707899, 2024). "As expected, CLP sepsis in WT mice caused significantly increased expression of both CXCL-1 and CCL2 compared to sham control." (PMID 35625756, 2022). "In the present study, we found that ABR-238901 attenuated sepsis-associated CXCL1 and CXCL2 formation by more than 50% and 38% in the lung." (PMID 34884728, 2021). "Key pro- and anti- inflammatory mediators like IL-1α, MIP-1β, RANTES, CXCL-1, IL-6 and IL-10, implicated to play a role in sepsis were up-regulated at both the early and late time points." (PMID 23009705, 2012). "This peritoneal vicious cycle that includes NET formation, IL-17A, CXCL-1/CXCL-2 that may amplify sepsis-associated organ injury." (PMID 41588042, 2026). "CXCL1 was linked with IL-17 production and Th17 cell regulation, with an important role in neutrophil recruitment and bacterial clearance in a mice polymicrobial sepsis and S. pneumonie-derived sepsis model." (PMID 40076848, 2025). "Moreover, the Ythdf1−/− mice were more susceptible to LPS-mediated sepsis in vivo, evidenced by increased CXCL1 mRNA expression in the lung." (PMID 40092485, 2025). "Using a mouse model of pneumonia-derived sepsis caused by Streptococcus pneumoniae, it was in fact shown that the CXCL1-mediated increase of neutrophil influx can be impactful to mouse survival by controlling bacterial growth and dissemination, and improving host survival." (PMID 38750020, 2024). "However, CXCL1 expression is also linked to many adverse conditions associated with uncontrolled inflammation and tissue damage, such as sepsis-associated encephalopathy, sepsis-associated acute kidney injury, and sepsis-induced lung injury." (PMID 37946314, 2023). "While the mechanism behind CXCL1 mediated anti-hyphal activity in our model is unknown, neutrophils from Cxcl1-deficient mice have an impaired reactive oxygen response in a polymicrobial sepsis model." (PMID 25629406, 2015). "CXCL1/KC produced by the liver also causes myeloid-derived suppressor cells (MDSC) mobilization which contributes to the control of systemic inflammation—a mechanism that may mitigate the course of sepsis." (PMID 36613652, 2022). "To elucidate the primary cellular source of CXCL1 in sepsis‐induced lung injury, we performed multicolor immunofluorescence co‐staining analysis on lung tissue sections from CLP mice." (PMID 40953301, 2025). "We also found a reduction in TNF‐α and CXCL1 levels in the plasma and peritoneum of bosutinib‐treated mice with sepsis." (PMID 40292988, 2025). "Next, we studied TNF‐α and CXCL1 levels in mice with CLP‐induced sepsis and how bosutinib treatment influences those levels in the plasma and peritoneum of septic mice." (PMID 40292988, 2025). "Sixty-nine significant associations between genetic loci and the clustered traits originated from candidate gene studies with replication, including associations such as ADCYAP1R1 with survival,22BCL2 with kidney failure, and CXCL1 with infection/sepsis." (PMID 40168842, 2025). "Specifically, we report here that CLP-sepsis caused a significant increase in IL-1β, IL-6, CCL3, CLL4, CXCL1, CXCL10 and GM-CSF, all of which contribute to sepsis-induced cytokine storm and, hence, to cardiac and organ dysfunction." (PMID 39559354, 2024). "Sepsis often leads to ileus, associated with TLR4 activation on myocytes in the ileum, a process which leads to an increase in CXCL1/KC expression in mice." (PMID 36613652, 2022). "In the brains of individuals who died from sepsis, expression of CXCL1 was significant in two out of three reported cases, although increased expression of CXCL8/IL-8 was observed in all three cases." (PMID 36613652, 2022).